RNU6-1230P (RNA, U6 small nuclear 1230, pseudogene)
Gene: Small nuclear RNA gene on chromosome 4 (149,934,376 to 149,934,483, forward strand). Ensembl gene ENSG00000207121.
Homologues: Orthologues: chimpanzee U6 (95% identical), macaque U6 (94% identical), rabbit U6 (75% identical), rabbit U6 (70% identical). Paralogues in human: RNU6-116P (89% identical), RNU6-25P (88% identical), RNU6-29P (88% identical), RNU6-33P (88% identical), RNU6-38P (88% identical), RNU6-41P (88% identical), RNU6-639P (88% identical), RNU6-1 (87% identical), RNU6-10P (87% identical), RNU6-15P (87% identical), RNU6-2 (87% identical), RNU6-30P (87% identical), and 1286 more.